PPARG (peroxisome proliferator activated receptor gamma)
Diseases named in the same sentence as PPARG in open-access papers (continued):
Sharing a sentence is not in itself a finding about the gene and the disease.
diabetes (continued). "Drugs that act on the arachidonic acid soluble epoxide hydrolase (sEH) enzyme combined with PPARγ and FXR agonism have been developed to treat cardiovascular diseases, diabetes, and kidney diseases." (PMID 37427406, 2023). "In this study, through bioinformatics analysis, we screened seven DCRGs, including PPARG, MMP9, CTNNB1, TNF, TGFB1, PTGS2, and HIF1A, and established a DCIN to comprehensively understand the diabetes-inflammation-cancer interaction." (PMID 37033970, 2023). "After comparing the diabetes related targets of GQD with cell proliferation targets, 4 potential targets (PPARG, TNF, INSR, CDK4) were selected for GQD." (PMID 35858880, 2022). "The mRNA concentrations of PPARγ and GLUT-4 (two proteins documented as key diabetes targets) were increased by 3T3-L1 adipocytes treated with compounds 1–4, but an absence of in vitro expression of PPARα was observed." (PMID 35056159, 2022). "Since thiazolidinedione-based precision medicine may be beneficial for patients with PPARγ variant-induced diabetes (PPARG-DM), it is necessary to determine the prevalence of PPARG-DM and develop clinical strategies for screening this condition." (PMID 34764936, 2021). "Muscle aging (Atrogin 1 and Glb1), diabetes (RAGE and CD163), and intracellular lipid accumulation (CD36 and PPARγ) related mRNA and protein expressions and FMOD were analyzed in MSTN knockout gas muscles." (PMID 34440852, 2021). "Further, we provide data that specific age‐related learning and memory can be enhanced with the diabetes pharmacotherapy, RSG PPARγ agonism even in WT mice." (PMID 33382528, 2021). "In both T1D and T2D, we found enrichment of monogenic forms of diabetes, as expected —2 genes in T1D (RASGRP1, INS) and 8 in T2D (HNF1B, GCK, WFS1, KCNJ11, ABCC8, HNF1A, PPARG, SLC2A2)." (PMID 33836063, 2021). "For example, in the TF–miRNA regulatory network of diabetes mellitus, we found all of the TFs (FOS, PPARG, HNF1B) with high degree centralities were validated to be associated with diabetes mellitus in related publications." (PMID 30371815, 2019). "A recent study suggested that PPARγ activation may decrease the progression of atherosclerosis and increase insulin sensitivity, and may be a potential therapeutic target for the treatment of various diseases, including type 2 diabetes mellitus and dyslipidemia." (PMID 30818882, 2019). "In majority of the herbal products and secondary metabolites used in treating diabetes, the mechanisms of action involve regulation of insulin signaling pathways, translocation of GLUT-4 receptor and/or activation the PPARγ." (PMID 28729836, 2017). "In conclusion, STAMP2 gene overexpression significantly downregulated the angiogenesis of EWAT and BAT via the PPARγ/CD36 signalling pathway, contributing to the improvement of IR and providing a new treatment target for diabetes and related diseases." (PMID 28631352, 2017). "PPARγ regulates how the body uses fats and sugars, and PPARγ agonist medications such as rosiglitazone and pioglitazone (glitazone [GTZ] drugs) are used to treat people with diabetes, a condition characterized by high levels of sugar in the blood." (PMID 26196151, 2015). "In conclustion, GB extract feeding inhibits the decrease of expression of FOXO1 and PPARγ, and increases insulin signaling, contributing to the improvement of insulin sensitivity in aged mice.Therefore, GB extract might have a potential to ameliorate age-related metabolic disorder such as diabetes." (PMID 25912041, 2015). "Analysis performed in rats, where diabetes was induced with streptozotocin (STZ), suggested the tissue specific effects – expression of PPARγ was increased in aorta, but decreased in renal cortex or retina." (PMID 25361524, 2014). "Further research is required to understand the full impact of KDT501's PPARγ and AGTR2-mediated mechanisms and their functional roles in diabetes." (PMID 24498211, 2014).
diabetes (continued). "PPARγ agonists also lower blood pressure and decrease circulating PAI-1 and CRP levels in patients with diabetes." (PMID 24524207, 2014). "The use of natural [e.g., relaxin] or synthetic PPARγ activators, or strategies directed to increase PPARγ expression or activity in the uterine vasculature may have important therapeutic potential in treatment of pregnancies complicated by hypertension, diabetes or preeclampsia." (PMID 23888144, 2013). "Accumulating evidence suggests important connections between Nrf2, PPARγ, and PI3K/Akt on regulating antioxidant enzymes in diabetes." (PMID 23737653, 2013). "Cordycepin decreased diabetes regulating genes such as 11β-HSD1, RANTES, and PPARγ in activated macrophages." (PMID 20107539, 2009). "To test this possibility, we analyzed methylation of the PPARγ promoter in white adipose tissues (WAT) and compared the methylation profiles of the promoter in wild-type mice and mouse models of diabetes." (PMID 19589179, 2009). "The results of molecular docking indicated that the active ingredients of Jerusalem artista might be combined with PPARG and STAT3 to treat diabetes, and the results of molecular docking further proved the accuracy of the network pharmacological screening." (PMID 41189218, 2025). "Additionally, antioxidantpolyphenols obtained from some plants can increase PON1 expression by activatingPPARγ, suggesting astrong correlation between PPARγ and PON1 in diabetes." (PMID 40834279, 2025). "PPARG mutation carriers were also more likely to be born preterm, regardless of maternal diabetes status, which further supports the role of fetal PPARG in placental development." (PMID 38633783, 2024). "Given the well-established molecular link between Sirt1 and PPARG signaling and the detrimental role played by PPARG in the context of MCM, we examined PPARG and PPARG-dependent genes LPL, PLIN, CD36, FAS and PPARA in cardiac specimens from diabetics and controls." (PMID 37957697, 2023). "These vascular anti-inflammatory and organ protective actions of PPARγ improve vascular function in patients with atherosclerosis and hypertension with or without diabetes." (PMID 37427406, 2023). "While PPARγ agonists are FDA-approved drugs for Type 2 Diabetes Mellitus, their safety during pregnancy is not yet established." (PMID 37299422, 2023). "Some glycosidic compounds prevent diabetes by targeting the sodium-dependent glucose cotransporter (SGLT), dipeptidyl peptidase IV (DPP-IV), glucagon-like peptide 1 (GLP1), and peroxisome proliferator-activated receptor gamma (PPARγ)." (PMID 35268062, 2022). "Many molecules are involved in islet function and the pathogenesis of diabetes, including CD36, glucose transporters (GLUT) 2, insulin receptor substrate (IRS) 1, IRS2, pancreatic and duodenal homeobox 1 (PDX1), and peroxisome proliferator activated receptor gamma (PPARG)." (PMID 35343389, 2022). "Impaired activity of PPARγ has been found in the setting of diabetes with and without cardiovascular diseases, PD, and LC cells." (PMID 35153741, 2021). "Upregulation of PPARg expression/activity has been reported to improve insulin sensitivity and glucose uptake through GLUT 4 translocation pathway in human adipocytes and in animal models of diabetes." (PMID 32258479, 2020). "Among them, the thiazolidinediones, acting on the nuclear transcription factor peroxisome proliferator-activated receptor gamma (PPAR)-γ and thus true insulin sensitizers drugs, have demonstrated the best efficacy, improving liver histology in NASH independently from the presence of diabetes." (PMID 31010049, 2019). "Then Our study found that exercise-induced decreases of chemerin/CMKLR1 in the livers and gastrocnemius were mediated via PPARγ, and exercise plus PPARγ agonist was more effective than exercise alone in decreasing chemerin/CMKLR1 and improving glycolipid metabolism of diabetes rats." (PMID 30873215, 2019).
diabetes (continued). "The mRNA of adiponectin, which is one of the key compounds in the treatment of diabetes, is expressed by the binding of retinoid X receptor (RXR) and activated PPARγ to peroxisome proliferator response element (PPRE) and Liver Receptor Homolog-1 (LRH-1) binding to LRH-RE on DNA." (PMID 31878261, 2019). "CDKAL1, RREB1, and PPARG were not significant in either arm of the diabetes stratified analysis, while RAI1 and SLC9B2 were significant in the non-diabetes group." (PMID 31451708, 2019). "Rosiglitazone (RSG) is a kind of peroxisome proliferator-activated receptor-gamma (PPAR-γ) agonist, commonly used to treat type 2 diabetes mellitus (T2DM), which could enhance insulin sensitivity (Hiatt, Kaul & Smith, 2013)." (PMID 31637120, 2019). "APS has reported to significantly enhance the gene expression of peroxisome-proliferator-activated receptor gamma (PPAR-γ) in a concentration-time dependent manner and stimulated superoxide dismutase (SOD) anti-oxidative mechanism in type-1 diabetes mellitus (DM) models." (PMID 31374889, 2019). "This study was designed to assess whether the protective effects of bone marrow-derived mesenchymal stem cells (MSCs) against diabetes could be enhanced by pioglitazone (PIO), a PPARγ agonist." (PMID 29959408, 2018). "PPARγ also has a critical role in systemic fluid retention through the regulation of renal sodium transport in the collecting duct, as the adverse effect of TZD use in the treatment of diabetes is PPARγ-dependent." (PMID 30012954, 2018). "It has been shown that activation of PPARγ by pioglitazone can attenuate cardiac fibrosis and partly ameliorate cardiac remodeling and function by suppressing activity of RAS, in a rat model of diabetes." (PMID 29312293, 2017). "Pioglitazone downregulates RAGE expression and inhibits ROS production and NF-κB activation via PPARγ activation, which may prevent the inflammatory effects of the AGE/RAGE system in diabetes." (PMID 28883907, 2017). "In majority of the herbal products and secondary metabolites used in treating diabetes, the mechanisms of action involve regulation of insulin signaling pathways, translocation of GLUT-4 receptor and/or activation the PPARγ as well as anti-inflammatory and immunomodulatory action." (PMID 28729836, 2017). "For example, in murine model of diabetes, activation of PPARγ by nitro-FAs restored insulin sensitivity and blood glucose levels and in experimental models of COPD, treatment with PPARγ agonists contrasted cigarette smoke-induced inflammation and downregulation of HDAC2." (PMID 26339618, 2015). "PIO downregulated RAGE expression and inhibited ROS production and NF-κB activation via PPARγ activation, which may prevent the inflammatory effect of AGE/RAGE system in diabetes." (PMID 25523934, 2015). "PPARγ agonists attenuate nephropathy in experimental models of anti-GBM-GN, lupus erythematosus, type 2 diabetes, and non-diabetic glomerulosclerosis, and decrease proteinuria in patients with type 2 diabetes and non-diabetic renal disease." (PMID 25785827, 2015). "In diabetes mellitus, long-term activation of PPARγ by thiazolidinediones not only reduces glycaemia and insulinemia but also attenuates vascular dysfunction." (PMID 24524207, 2014). "Another small open study in 32 patients with both mild-to-moderate AD (or amnestic MCI) and diabetes mellitus not on insulin randomised patients between the PPARγ agonist pioglitazone or no additional treatment." (PMID 25385407, 2014). "In summary, activation of PPARγ by rosiglitazone improves angiogenic potential of diabetic ECs and PACs, but decreased expression of PPARγ in diabetes does not impair angiogenesis." (PMID 25361524, 2014). "Moreover, thiazolidinediones such as rosiglitazone have been shown to reduce endothelial RAGE expression in patients with diabetes, suggesting a possible feedback loop in our model, as we demonstrated that RAGE is an upstream mediator of PPARγ." (PMID 23525442, 2013).
diabetes (continued). "In this study, we investigated the correlation between the PPARγ C161→T and the occurrence of CAD in a Chinese Han population with or without T2DM, in order to determine a possible genetic marker to predict the development of CAD in patients with diabetes." (PMID 20334678, 2010). "Serum FSH and LH were not significantly altered by activation of PPARγ with rosiglitazone and/or by diabetes (P > .05)." (PMID 19536350, 2009). "Previous studies have shown that rutin can improve diabetes by inhibiting the activities of α-glucosidase and α-amylase, activating the synthesis of transporter GLUT-4, increasing the expression of PPARγ, reducing hepatic G6Pase, and increasing hexokinase activity." (PMID 40076380, 2025). "Although TZDs used in patients with type 2 diabetes mellitus may theoretically alleviate inflammation via the activation of PPARγ, such a benefit has not been well demonstrated in humans." (PMID 37242462, 2023). "The FDA-approved thiazolidinedione class of drugs for treating diabetes attenuate the AGE-RAGE interactions through an indirect mechanism: they inhibit the formation of RAGE and induce the expression of s-RAGE through the activation of the peroxisome proliferator-activated receptor gamma (PPAR-γ)." (PMID 36144449, 2022). "Similarly, PPARγ, a transcription factor in the PPAR protein family and a target of TZDs, diabetes drugs also known as glitazones, has beneficial effects on glycemic control while simultaneously promoting cholesterol efflux from macrophages, similar to the activity of HDL cholesterol." (PMID 33828528, 2021). "Therefore, maybe there are functional connections between BRCA1, PPARγ and PFKP in glycolysis system and PFKP inhibitor may have a potential effect on BRCA1 dysfunctional breast cancer patients who suffer from diabetes and need treatments with PPARγ agonists." (PMID 32470015, 2020). "However, if pioglitazone and GW9662 still influenced PPARγ expression in exercised diabetes rats, whose PPARγ expression were increased, have not been confirmed." (PMID 30873215, 2019). "To date, only scattered evidence is available at the clinical level for a potential therapeutic value of PPARγ agonists in MS, with reports available exclusively about pioglitazone, a drug approved by the Food and Drug Administration (FDA) for the treatment of type 2 diabetes mellitus." (PMID 30669473, 2019). "Our data clearly confirmed the beneficial effects of DKE on PPARγ activation and FOXO1 deactivation in both the in vivo and the ex-vivo models and thus, scientifically approved the validity of the traditional use of DKE against diabetes and some of its complications." (PMID 30376839, 2018). "It has been reported that peroxisome proliferator-activated receptor gamma (PPARG) and peroxisome proliferator-activated receptor gamma co-activator 1 (PPARGC1) family (e.g. PPARGC1A and PPARGC1B) are key agents in the development and pathophysiology of type 2 diabetes mellitus (T2DM)." (PMID 28418876, 2017). "As an example, some of the lipid-lowering effects of PPARγ agonists, attributable to defects in fatty acid use or storage are only observed in the context of diabetes, but not in nondiabetic atherosclerotic models in which the dyslipidemia is caused, for example, by defective ApoE." (PMID 25785279, 2015). "However, the role of the RAAS in mediating vascular protective effects of PPARγ-agonists is presently not fully understood, particular not in metabolic condition of diabetes." (PMID 23374104, 2013). "Furthermore, PPARγ agonist rosiglitazone seems to enhance carcinogenic effects of the urinary bladder in rodents, while treatment of diabetes with pioglitazone in humans does not seem to increase the incidence of these or any other tumors." (PMID 20182546, 2010). "Neither diabetes nor PPARγ activation with rosiglitazone adversely altered serum E2." (PMID 19536350, 2009). "Neither diabetes nor PPARγ activation altered serum E2 or gonadotropins FSH and LH concentrations." (PMID 19536350, 2009).
diabetes (continued). "PPARγ affects inflammation directly, bydriving CD36-dependent apoptosis in MΦs, or indirectly, by reducing VCAM-1expression by the ECs and thus blocking transendothelial migration (TEM) ofmonocytes and MΦs during chronic inflammation typicalfor diabetes and cancer." (PMID 19043603, 2008). "There have been relatively few studies of PPARγ agonists in patients without diabetes." (PMID 15892894, 2005). "However, sex differences related to PPARγ have been observed in human T cells, alongside changes in the expression of PPARα, and in fetal mice in nutritional programming studies and parental diabetes with no change in PPARα." (PMID 40829644, 2025). "This study aimed to assess whether the simultaneous activation of PPARγ and inhibition of SGLT2 cotransporters provide additive protection against inflammation and fibrosis which are highly engaged in the progression of DN in experimental type 1 diabetes mellitus." (PMID 41006906, 2025). "Besides being implicated in obesity, CABLES1 could potentially also play a role in the development of diabetes through its role as an adaptor protein for CDK5, which has been shown to control diabetogenic actions of PPARG, a master regulator of adipogenesis and crucial for adipocyte function." (PMID 37555665, 2023). "PPARγ functions as the master regulator of glucose homeostasis and lipoprotein metabolism, and recent studies have reported that it is involved in various metabolic diseases such as diabetes mellitus, hyperlipidemia, coronary artery disease (CAD), and nonalcoholic fatty liver disease (NAFLD)." (PMID 35547362, 2022). "Interestingly, PPARG agonists have been used in the treatment of dyslipidemia and hyperglycemia and many insulin sensitizing drugs targetting PPARG are designed in the treatment of diabetes as a way to lower serum glucose without increasing pancreatic insulin secretion." (PMID 24391967, 2013). "These agonists can improve insulin signaling, regulate glucose and lipid metabolism, and offer protection against Type 2 diabetes mellitus (T2DM) by stimulating AMPK activity in adipose tissue, liver, and muscle, irrespective of PPARγ activation." (PMID 40430476, 2025). "In 2014 the same authors demonstrated that the phosphorylation of PPARγ-Ser245 by CDK5 did not alter its adipogenic activity but dysregulated a specific set of genes with roles in obesity and diabetes." (PMID 37189440, 2023).